ENSG00000284292 (novel protein, ARPC1A and ARPC1B readthrough)
Gene: Protein-coding gene on chromosome 7 (99,325,879 to 99,394,653, forward strand). Ensembl gene ENSG00000284292.
Genetic constraint (gnomAD): Loss-of-function variants: 36 observed, 82.64 expected, observed/expected ratio (o/e) 0.44, 90% interval 0.33 to 0.57. Missense variants: 704 observed, 950.8 expected, observed/expected ratio (o/e) 0.74, 90% interval 0.69 to 0.79. Synonymous variants: 325 observed, 362.26 expected, observed/expected ratio (o/e) 0.9, 90% interval 0.82 to 0.98.